FTO (FTO alpha-ketoglutarate dependent dioxygenase)
Diseases named in the same sentence as FTO in open-access papers (continued):
Sharing a sentence is not in itself a finding about the gene and the disease.
Obesity (continued). "In this review, we comprehensively discuss the correlation between obesity and cancer by measuring FTO gene polymorphism, as well as the molecular mechanism involved in these diseases, emphasizing FTO as the common genetic basis of obesity and cancer." (PMID 33304380, 2020). "FTO is a significant fat mass and obesity associated gene with a full length of 400 kp, including nine exons, which mainly locates in the 16q12-q24 of the human chromosome." (PMID 32110378, 2020). "The Balinese population showed a high MAF of the FTO rs9939609 and rs1421085 risk alleles that were associated with increased BMI and obesity." (PMID 31915589, 2020). "Several studies reported that FTO genotype has a strong association with body mass index (BMI) and obesity." (PMID 32843047, 2020). "Earlier GWAS studies led to the discovery of FTO rs9939609 genetic variant in association with obesity among Europeans." (PMID 31024458, 2019). "In this context, there is an urgent need to decipher the causal mechanism for the role of FTO noncoding variants in the aetiology of obesity and its related disorders." (PMID 32076432, 2019). "For example, although FTO was reported as a susceptibility gene for obesity, the effector genes whose expression levels were influenced by the significantly associated SNPs were not FTO but Iroquois Homeobox 3 (IRX3) and IRX521." (PMID 30643196, 2019). "Several studies indicated that the fat mass and obesity-associated (FTO) gene, especially the FTO rs9939609 variant, has a relationship with body weight and fat mass." (PMID 31200723, 2019). "One of the genes that has been identified to have variants associated with obesity was the fat mass and obesity-associated gene (FTO)." (PMID 31695458, 2019). "Rs7205859, in the promoter flanking region immersed in intron 1 of FTO, was the only variant associated to BD and obesity (p < 0.05)." (PMID 31033179, 2019). "The polymorphisms of Omentin Val109Asp (rs2274907) and FTO rs9939609 genes are of high importance in overweight, obesity, and T2D." (PMID 31200723, 2019). "In Chinese population, Genetic variation in the FTO gene is strongly associated with obesity and BMI, and its effect size on BMI is comparable with that in the European population." (PMID 31509542, 2019). "The amount of FTO gene expression in various tissues is also linked to body fat percentage and obesity." (PMID 31447604, 2019). "Two loci associated with ESKD have been previously associated with obesity traits (FTO and IRX3), but our SNVs are low frequency and more common in African ancestry." (PMID 31178898, 2019). "It is worth mentioning that since Frayling first proposed in 2007 that fat mass and obesity associated (FTO) gene is associated with obesity, a large number of studies have been carried out around the world to confirm the relationship between FTO gene and BMI." (PMID 31731772, 2019). "In this study, we evaluated the influence of the FTO rs1421085 variant on various anthropometric and body composition measures and obesity, inflammatory, and cardiovascular biomarkers in a cohort of Kuwait Arab subjects." (PMID 32076432, 2019). "In mice, the loss of the FTO gene causes postnatal growth retardation, and FTO overexpression leads to increased food intake and obesity." (PMID 31998272, 2019). "The FTO gene is also known as the ‘fat mass and obesity-associated gene’ since it has been shown to impact weight management and body composition." (PMID 30838211, 2019). "In a study, genetic variations (rs17817449 and rs142085) occurring in the loci of the FTO gene were reported to contribute to the etiology of obesity by increasing the level of plasma leptin and causing the insulin resistance." (PMID 31810473, 2019). "Despite the association of many FTO genetic variants with obesity traits in humans, elucidation of the mechanistic basis for these associations has been elusive." (PMID 32076432, 2019).
Obesity (continued). "RPGRIP1L represents a particularly interesting target, as its expression and activity are regulated by intronic variants located in the FTO gene (which is strongly associated with obesity and T2D) through long-range regulation." (PMID 31754094, 2019). "Several studies indicate that polygenic obesity is linked to fat‐mass and obesity‐associated (FTO) genetic variants." (PMID 31033179, 2019). "In the current study, the aim is to explore the potential effect of two FTO SNPs rs9939609 and rs9930506, strongly linked to obesity, on the pattern of food intake in the Emirati population." (PMID 31622411, 2019). "The observations underscore varying FTO -linked risk in the manifestation of population specific epidemiology of genetically bound obesity." (PMID 30871540, 2019). "The FTO gene has been reported to influence food cravings, with individuals carrying the obesity-susceptible A allele having higher total food cravings compared to TT homozygotes which correlates with higher BMI." (PMID 30759834, 2019). "The fat mass and obesity-associated (FTO) gene is a significant genetic contributor to polygenic obesity." (PMID 31075924, 2019). "The 45–50% heterozygous subjects maintain risk as well, while only around 28% of population doesn’t have any of the obesity risk SNP alleles in FTO intron 1 genotype." (PMID 30871540, 2019). "It was determined that the risk of obesity was 1.67 times higher in individuals with homozygous FTO gene risk alleles, and this relationship was caused by an increase of fat mass specifically from the age of 7 years." (PMID 31810473, 2019). "The fat mass and obesity-associated (FTO) gene [chromosome 16 (16q12.2a)] has shown the largest effect on BMI, although the increase is modest." (PMID 31622411, 2019). "Some genes such as the fat mass and obesity-associated (FTO) gene are reported to be strongly associated with obesity and overweight after the age of 7 y." (PMID 31771407, 2019). "The fat mass and obesity-associated (FTO) gene variants rs1121980, rs17817449, rs8050136, rs9935401, rs3751812, rs9939609, rs9930506, and rs9922708 were previously associated with obesity." (PMID 31075924, 2019). "Polymorphisms in the fat-mass obesity (FTO) gene have been consistently found to be associated with obesity, and recently found to increase the risk of developing MS." (PMID 31836807, 2019). "Based on the association of obesity with MS risk and the established association of FTO rs9939609 with obesity, investigating obesity genes in relation to MS should be conducted to understand the mechanism underlying the link between the two diseases." (PMID 31836807, 2019). "Genome-wide association studies have identified single-nucleotide polymorphisms (SNPs) in the first intron of the fat mass and obesity-associated (FTO) gene also known as alpha-ketoglutarate-dependent dioxygenase." (PMID 31695458, 2019). "Some researches verified that PGM1 (Phosphoglucomutase-1) and FTO (Fat mass and obesity-associated protein) that located on chromosome 6 significantly affected muscle development and obesity, respectively." (PMID 31024621, 2019). "One example concerns the fat mass and obesity associated (FTO) gene, which was the topic of a recent systematic review that promulgated FTO gene as a possible mediator for the association between obesity and breast cancer." (PMID 31555578, 2019). "Of the 47 subjects, 15 were of normal risk for obesity whereas 32 were carriers of the FTO gene risk alleles." (PMID 31477138, 2019). "Variations in the fat mass and obesity-associated gene (FTO) are associated with obesity; however, it is unclear if changes in energy intake affect the adaptive response to caloric restriction in those with risk variants." (PMID 31477138, 2019). "People who have the risk allele in the polymorphisms of the FTO gene (e.g. rs9939609 & rs9930506) have a greater risk of developing obesity." (PMID 31447604, 2019).
Obesity (continued). "The aim of the current study is to explore the potential effect of fat mass and obesity-associated protein gene (FTO) rs9939609 and rs9930506 single nucleotide polymorphism (SNP) on the pattern of food intake in the Emirati population." (PMID 31622411, 2019). "We analyzed the population specific haplotype profiles of FTO genomic locus identified by Genome Wide Association Studies (GWAS) for the high obesity risk by examining eighteen 1000G populations from 4 continental groups." (PMID 30871540, 2019). "The study aimed to identify fatty acid synthase (FASN), LOC514211, and fat mass and obesity-associated (FTO) gene polymorphisms and to investigate their associations with milk traits in an Indonesian-Holstein dairy cow population." (PMID 31528048, 2019). "For example, an obesity-associated FTO variant (rs1421085) was found to disrupt an ARID5B repressor motif in an enhancer for IRX3/IRX5 during adipocyte differentiation, increasing obesity risk." (PMID 30617125, 2019). "Our results suggest a possible effect of FTO variants on neurodevelopment in obesity and bipolar disorder, which gives new insights into the molecular mechanism underlying this association." (PMID 31033179, 2019). "In many GWASs in the literature, besides the determination of the frequencies of FTO genotypes, the expression levels were also investigated, and an increased expression level was found to increase the risk of obesity by affecting these parameters." (PMID 31810473, 2019). "For instance, five PC metabolites (PC aa C 36:5, 36:6, 38:5, 38:6, and 40:6) are associated with obesity and type 2 diabetes based on FTO genotype in the Korean population." (PMID 31426326, 2019). "Single-nucleotide polymorphisms (SNPs) that cluster in the first intron of the FTO gene show the strongest association with BMI (∼0.35 kg/m2 per allele), and obesity risk." (PMID 30759834, 2019). "We assessed the relationship between the common FTO gene polymorphism and obesity status in MS patients after adjusting for both age and gender." (PMID 31836807, 2019). "The significance of these findings is that these genes such as FTO has been associated with weight gain and BMI; and is well-known risk factor of obesity." (PMID 32010189, 2019). "In aggregate, it was revealed that FTO SNPs were not only associated with obesity and type 2 diabetes but also with the BMD at the hip." (PMID 31998240, 2019). "An obesity linked protein coding variant rs1421085 in the FTO gene has previously been defined as a heterozygous risk factor modifier." (PMID 31604968, 2019). "The GWAS studies identified strong signals within intron 1 of the FTO gene associated with an increase in T2D, body mass index (BMI), and obesity." (PMID 31482095, 2019). "Clinical studies have demonstrated a strong association between a single-nucleotide polymorphism in the FTO gene and obesity in diverse ethnic populations." (PMID 31728912, 2019). "Here we show that N6-methyladenosine (m6A) mRNA demethylation by fat mass and obesity-associated protein (FTO) increases melanoma growth and decreases response to anti-PD-1 blockade immunotherapy." (PMID 31239444, 2019). "Of particular interest has been the fat mass and obesity-associated (FTO) gene, with those homozygous for A-allele demonstrating an association with body mass index (BMI), waist circumference, type 2 diabetes (T2D), and other obesity-related traits." (PMID 31635368, 2019). "They reported that genetic variations in the loci of the FTO gene (rs9939609, rs17817449, and rs142085) contribute to the aetiology of obesity by affecting the level of plasma leptin and causing insulin resistance." (PMID 31810473, 2019). "The results showed that 21.8% of the participants with overweight/obesity had FTO A allele, while 7.8% of the individuals with normal BMI had FTO A allele." (PMID 31200723, 2019). "In this study we report an association between FTO rs9939609 gene polymorphism and risk of obesity in a cohort of MS patients." (PMID 31836807, 2019).
Obesity (continued). "The results imply that the FTO locus is one of the major genetic determinants for obesity risk from GWAS SNPs set." (PMID 30871540, 2019). "Recent studies have also examined the interactive influence of FTO variants and lifestyle factors on obesity risk." (PMID 31075924, 2019). "Further, the authors observed that physically inactive individuals carrying the A allele of rs8050136 FTO SNP had 1.89 times significantly increased risk of obesity compared to those with CC genotype (Pinteraction = 4.0 × 10−5)." (PMID 31024458, 2019). "Efforts have been made to understand the biological mechanisms underlying body weight regulation: SNPs in FTO are believed to be associated with obesity through an effect on RPGRIP1L." (PMID 31075924, 2019). "Here, we found that some DMR genes are obesity genes or related to the former which have been studied by genomic and genome-wide association study (GWAS) methods, for example, FTO, PCSK5, PCSK6, NTRK2, ABCC4, TXNIP and RPS6KA2." (PMID 31637123, 2019). "Because NAFLD is closely linked to obesity, we also explored the specific SNP × SNP interaction of the major obesity locus, FTO (rs1421085) and PNPLA3 (rs738409)." (PMID 31311600, 2019). "Early genome-wide association studies (GWAS) associated FTO genetic variants with obesity traits in Europeans; subsequently, many of these risk variants were replicated in Africans, South and East Asians, and other populations." (PMID 32076432, 2019). "Different to other studies, which have found interactions especially between variants of the fat-mass and obesity-associated FTO gene, the variant of the FTO gene used in the present study did not belong to the SNPs with strongest interaction effect." (PMID 31442235, 2019). "Since FTO is one of the essential genes associated with obesity signaling, we determined further that the decrease of FTO gene expression also corresponded to a reduction at the protein level." (PMID 31554925, 2019). "FTO is the first GWAS-identified obesity-susceptibility locus and shows the strongest association with BMI in our pediatric cohort." (PMID 31285522, 2019). "A cross-sectional study on 4,839 Swedish people showed that the relation between FTO gene polymorphisms and obesity can be seen only in people who have a high rate of fat and low rate of carbohydrate intake." (PMID 31447604, 2019). "In recently conducted many GWAS, one of the major causes of obesity has been reported to be the FTO gene polymorphism (rs9939609)." (PMID 31810473, 2019). "It has been reported that FTO risk allele contributes 20% to the obesity cases seen in the Caucasian population." (PMID 31810473, 2019). "Previously, FTO was known to be highly associated with increased body mass and obesity in childhood and adult." (PMID 30922314, 2019). "This had a minor impact on AUC value (AUC = 0.582, p = 0.036), suggesting that the remaining SNP in LGI-Ob model had major influence with the inflammatory profile associated with obesity than FTO per se." (PMID 30704070, 2019). "The single-nucleotide polymorphism (SNP) rs3751812 in the fat mass and obesity-associated (FTO) gene was genotyped using the Illumina PsychArray BeadChip platform." (PMID 31772290, 2019). "The association of omentin rs2274907 (Val109Asp) and fat-mass and obesity-associated (FTO) rs9939609 gene polymorphisms with overweight/obesity and T2D is controversial." (PMID 31200723, 2019). "FTO rs9939609 shows the strongest association reported with obesity in several populations and ethnic groups." (PMID 30764545, 2019). "FTO was the first obesity-susceptibility gene identified through GWASs and continues to be the locus with the largest effect on BMI and obesity risk." (PMID 31220230, 2019). "Some studies in the literature show the contribution of rs17817449, rs3751812, rs1421085 and rs9930506, rs7202116 SNPs to the association between FTO and childhood/adult obesity." (PMID 31810473, 2019).
Obesity (continued). "(b) Genetics: there is substantial evidence that obesity clusters in families, and that some of this is associated with inherited genes (e.g., the FTO gene)." (PMID 29983415, 2019). "Among them, SNPs in intron 1 of the FTO gene are the more strongly associated with polygenic obesity in European, African and East Asian populations." (PMID 31772290, 2019). "This review study aimed to investigate the effect of fat mass and obesity-associated (FTO) gene in the association between dietary carbohydrates and cancer." (PMID 31447604, 2019). "Homozygosity for the A allele of FTO rs9939609 phenotypically correlates with an increase in BMI and adiposity and also increases the risk of obesity by 1.7 times when compared to subjects homozygous for the T allele." (PMID 31344895, 2019). "The variant (rs9939609) today has been consistently associated with obesity in multiple populations making FTO the most commonly studied obesity gene." (PMID 31836807, 2019). "It has also been suggested that the homeobox gene Iroquois homeobox 3 (IRX3) is a functional long-range target of obesity-associated variants within FTO." (PMID 31075924, 2019). "Despite the recognized relevance of FTO gene variants on obesity predisposition the relation between FTO expression in blood cells and biochemical or clinical parameters related to metabolic syndrome is not well-defined." (PMID 31064394, 2019). "An unweighted genetic risk score (GRS) was calculated for two FTO single-nucleotide polymorphisms (rs8050136 and rs2388405) by summation of the number of risk alleles for obesity." (PMID 31516636, 2019). "Fat mass and obesity-associated (FTO) gene has been under close investigation since the discovery of its high impact on the obesity status in 2007 by a range of publications." (PMID 30871540, 2019). "In an attempt to yield new insights of a possible mechanism underlying the association of FTO‐obesity risk variants with BD, we performed an in silico prediction algorithm consulting different databases." (PMID 31033179, 2019). "Consistent with the body weight results, we observed that the expression of the obesity-associated gene FTO was reduced in CTS-, COST-, and COSM-treated rats compared with HF rats." (PMID 31817377, 2019). "In this study, we analyzed a genetic association of FTO variants with BD and obesity using a variant aggregation strategy, and we also performed an in silico prediction analysis of the possible functional impact of these variants in the developing brain." (PMID 31033179, 2019). "Many genetic loci have been associated with obesity, and the FTO locus has the greatest effect size." (PMID 31126299, 2019). "We therefore assessed the common FTO gene polymorphism (rs9939609) in relation to obesity, risk of developing MS and its disability in a cohort of MS patients." (PMID 31836807, 2019). "The association between the FTO gene and obesity has been confirmed through the study of the FTO gene polymorphisms." (PMID 31447604, 2019). "FTO was originally identified as a regulator for body mass and obesity, as FTO’s deficiency resulted in growth retardation while overactivation of FTO increased food intake and led to obesity." (PMID 31827395, 2019). "In this context, a 2007 GWAS showed that fat mass and an obesity-related gene (FTO) variant are associated with type 2 diabetes and the gene’s effect on obesity can regulate this relationship." (PMID 31810473, 2019). "On the other hand, based on a body of evidence, the common rs9939609 polymorphism in the fat mass- and obesity-associated (FTO) gene is associated with higher BMI, risk of obesity, and subsequent T2D in different populations." (PMID 31200723, 2019). "One of the genes that has recently been featured in this context is the fat mass and obesity-associated (FTO) gene." (PMID 31447604, 2019).